AURKA (aurora kinase A)
Diseases named in the same sentence as AURKA in open-access papers (continued):
Sharing a sentence is not in itself a finding about the gene and the disease.
bladder cancer (continued). "Increased expression of LINC00958 and AURKA was observed in bladder cancer tissues and cell lines." (PMID 34702201, 2021). "Taken together, it can be concluded that miR-490-3p directly targets AURKA in bladder cancer cells." (PMID 34702201, 2021). "Consistent with previous reports, a similar molecular mechanism of AURKA in bladder cancer was revealed in our study; high level of AURKA was also observed in bladder cancer, and the downregulation of AURKA could hamper bladder cancer progression." (PMID 34702201, 2021). "Therefore, our study revealed a new axis involving LINC00958-miR-490-3p-AURKA in the progression of bladder cancer." (PMID 34702201, 2021). "Moreover, we identified aurora kinase A (AURKA) as a new downstream target of PUF60 in bladder cancer cells." (PMID 33117697, 2020). "Collectively, these results indicate that the PUF60/AURKA axis plays a key role in regulating tumorigenesis and progression of bladder cancer, and may be a potential prognostic biomarker and therapeutic target for bladder cancer patients." (PMID 33117697, 2020). "In bladder cancer, inhibiting AURKA by its specific inhibitors could decrease cell proliferation, induce apoptosis and cause cell cycle arrest." (PMID 33117697, 2020). "High expression of PUF60 and AURKA predicted poor prognosis in bladder cancer patients." (PMID 33117697, 2020). "Furthermore, we showed that there was a significant positive correlation between PUF60 and AURKA expression in bladder cancer tissues, and PUF60 and AURKA expression contributed to tumor progression and malignant phenotypes in the patients with bladder cancer." (PMID 33117697, 2020). "PUF60 promoted bladder cancer cell growth by activating AURKA signaling." (PMID 33117697, 2020). "Correlation between PUF60/AURKA and clinical pathology characteristics in bladder cancer." (PMID 33117697, 2020). "Moreover they emphasize that AURKA expression levels, as compared to urine cytology, are particularly effective for the detection of low-grade bladder cancers." (PMID 28102366, 2017). "We hypothesized that LINC00958 aggravates bladder cancer progression via the miR-490-3p-AURKA axis." (PMID 34702201, 2021). "Therefore, whether the Wnt/β-catenin pathway or other pathways participate in the LINC00958/miR-490-3p/AURKA axis in bladder cancer needs further exploration." (PMID 34702201, 2021). "Thus, the LINC00958-miR-490-3p-AURKA axis may be an effective therapeutic strategy for bladder cancer." (PMID 34702201, 2021). "Additionally, miR-490-3p, sponged by LINC00958, could regulate its target gene AURKA, thereby inhibiting the progression of bladder cancer." (PMID 34702201, 2021). "Collectively, our findings offer new insights into the understanding of the pro-tumorigenic role of PUF60 and its underlying mechanism involved in bladder cancer growth, and suggest that the PUF60/AURKA axis may provide prognostic biomarkers and therapeutic targets for bladder cancer patients." (PMID 33117697, 2020). "Targeting AURKA may afford a novel treatment approach to bladder cancer." (PMID 30547784, 2018). "We have also shown that a fluorescence in situ hybridization (FISH) test for AURKA copy number in cells from voided urine could be used to detect bladder cancer and that the quantitative assessment of AURKA copy number provides an estimate of bladder cancer aggressiveness." (PMID 28102366, 2017). "Finally, we show that the AURKA gene copy number could be used as an effective biomarker for the non-invasive detection of bladder cancer." (PMID 28102366, 2017). "Previous studies have demonstrated that TPX2 promotes AURKA activation and downstream PI3K/AKT signaling, thereby facilitating angiogenesis in bladder cancer cells." (PMID 40564876, 2025). "Hence, AURKA could be targeted by miR-490-3p to affect bladder cancer progression." (PMID 34702201, 2021).
bladder cancer (continued). "We found mRNA expression of AURKA, CDCA8, CDC20 were decreased upon knockdown of PUF60 by its specific siRNA, indicating that they are the potential downstream targets of PUF60 in bladder cancer (indicated by the arrows)." (PMID 33117697, 2020). "In in vitro studies, up-regulation of AURKA inhibited NNMT expression, which in turn contributed to bladder cancer invasion." (PMID 28102366, 2017). "To determine the relevance of these observations to human tumors, we measured the expression of AURKA and NNMT in 423 primary bladder cancers using immunohistochemistry and image analysis on tissue microarrays." (PMID 28102366, 2017). "Together, our results demonstrated that AURKA and NNMT play antagonistic roles in the regulation of invasion in bladder cancer cells in vitro." (PMID 28102366, 2017). "In urinary bladder cancer, STIL contributes to cell proliferation by inhibiting primary cilia formation through its interaction with AURKA, while in triple-negative breast cancer, it promotes malignancy by activating the Fanconi anemia pathway through KLF16 interactions." (PMID 39727708, 2024). "We further detected the AURKA concentrations in patients with healthy bladder (n = 40; Normal control), benign bladder disease (n = 10; NC group), and bladder cancer (n = 40; BLCA group)." (PMID 37101292, 2023). "Similarly, other studies observed that 5′-tRF-LysCTT was associated with advanced tumor phenotype and worse response to treatment in bladder cancer, while tRF-Leu-CAG promoted cell proliferation through the regulation of AURKA in NSCLC." (PMID 36982573, 2023). "Furthermore, our study showed that LINC00958 inhibited tumorigenesis in bladder cancer cells by suppressing miR-490-3p to upregulate AURKA, which was different from previous studies on LINC00958 in bladder cancer." (PMID 34702201, 2021). "Next, we treated RT4 and T24 cells with siRNA-AURKA (Si-AURKA), miR-490-3p inhibitor (inhibitor), and negative control (NC) to study the role of AURKA in bladder cancer." (PMID 34702201, 2021). "In addition, this study screened the differentially expressed miRNAs and mRNAs in bladder cancer using GEO DataSets, and the targets of LINC00958, miR-490-3p, and AURKA will be further explored in the future using multiple databases such as TCGA and GEPIA." (PMID 34702201, 2021). "In addition, we identified AURKA as a new downstream target of PUF60 in bladder cancer cells, and also proved that PUF60 promoted bladder cancer cell growth by transcriptionally upregulating AURKA expression." (PMID 33117697, 2020). "We should emphasize that although there is enrichment of the AURKA signature comprising its downstream target genes in basal bladder cancer not all AURKA overexpressing tumors show downregulation of NNMT." (PMID 28102366, 2017). "The analysis of several non-overlapping cohorts of patients with bladder cancer showed that there is a subset of patients characterized by overexpression of AURKA and down-regulation of NNMT with poor clinical outcomes." (PMID 28102366, 2017). "We initially tested the AURKA FISH probe on paired samples of voided urine and bladder tumor tissue from a cohort of 40 patients with bladder cancer that contained 14 patients with low grade transitional cell carcinomas (LGTCC) and 26 patients with high grade transitional cell carcinomas (HGTCC)." (PMID 28102366, 2017). "In conclusion, we believe that these five target genes (GSK3B, CDC20, TPX2, AURKA and CCNE1) may promote the occurrence of bladder cancer and lead to poor prognosis.We explored the potential therapeutic targets of aspirin for bladder cancer by comprehensive bioinformatics analysis." (PMID 36316768, 2022). "Thus, this study is the first to report that AURKA could be regulated by both LINC00958 and miR-490-3p in bladder cancer progression." (PMID 34702201, 2021). "Thus, we hypothesized that AURKA might be regulated by LINC00958-miR-490-3p, thereby affecting the malignant phenotypes of bladder cancer." (PMID 34702201, 2021).
bladder cancer (continued). "However, AURKA has not been previously studied in a ceRNA network involving an lncRNA in bladder cancer." (PMID 34702201, 2021). "Furthermore, AURKA depletion could reverse the malignancy phenotype, PC disassembly, and SHH signalling activation induced by STIL overexpression in BLCA cells, suggesting that STIL regulation for PC is dependent on AUKRA in bladder cancer." (PMID 37101292, 2023).
lung adenocarcinoma (28 papers, 2008 to 2024). A carcinoma that arises from the lung and is characterized by the presence of malignant glandular epithelial cells. "AURKA/nuclear factor kappa-light-chain-enhancer of activated B cells (NF-κB) signaling has been associated with radio-resistance in human lung adenocarcinoma." (PMID 33202573, 2020). "AURKA also was reported to be associated with poor prognosis of smoking related lung adenocarcinoma using bioinformatics analysis." (PMID 31781484, 2019). "By combining some studies, we found that the gene AURKA is a common targeted protein for both COVID-19 and lung adenocarcinoma patients." (PMID 36913345, 2023). "There is evidence that E3 ubiquitin ligase CBLC positively regulated the stability of AURKA via ubiquitination in lung adenocarcinoma." (PMID 36973424, 2023). "Consistently, miRNA-885-3p was found to decrease the expression of AURKA, which suppressed docetaxel chemoresistance in lung adenocarcinoma." (PMID 36064409, 2022). "In this work, NF-κB was identified as a downstream target of AURKA in SPC-A1/DTX cells linking NF-κB signaling with radio-resistance in human lung adenocarcinoma docetaxel-resistant cells." (PMID 33202573, 2020). "Liu and colleagues found that up-modulated AURKA was responsible for in vitro radio-resistance of docetaxel-resistant SPC-A1/DTX lung adenocarcinoma cells (SPC-A1/DTX)." (PMID 33202573, 2020). "In TCGA lung adenocarcinoma data sets there was a small, statistically significant increase in HURP, AURKA, TPX2 or RAN mRNA levels correlating with SMARCA4 mutations of all types." (PMID 28102363, 2017). "Immunohistochemical staining of stage I lung adenocarcinoma tissues demonstrated a positive correlation between AURKA expression and phosphorylation of EGFR at Thr654 and Ser1046 in EGFR-mutant specimens, but not in EGFR-WT specimens." (PMID 23520446, 2013). "In addition, we will further investigate the impact of downregulating or promoting FBP1, SBK1, and AURKA expression in PC9 cells on lung adenocarcinoma in the future." (PMID 37737707, 2023). "In our study, although, AURKA rs1047972 revealed negative results for altering CNS tumor risk, AURKA rs1047972 variants were identified to change lung adenocarcinoma (LADC) development probably." (PMID 35201446, 2021). "MKI67, PCNA, and AURKA are largely prognostic in the same cohorts with renal papillary cell carcinoma, lower-grade brain glioma, renal clear cell carcinoma, pancreatic adenocarcinoma, and lung adenocarcinoma." (PMID 32913979, 2017). "Yoo and colleagues recently showed that AURKA and AURKB confer an “invasiveness signature” in lung adenocarcinoma, indeed their simultaneous inhibition in vitro and in a murine model of lung adenocarcinoma reduced tumor invasion." (PMID 36387232, 2022). "Taken together, TSA was verified to suppress the progression of lung adenocarcinoma by inducing cell apoptosis, arresting cell cycle through regulating CCNA2-CDK2 complex and AURKA/PLK1 pathway." (PMID 34880385, 2021). "More direct evidence needs to be provided that TSA does indeed treat lung adenocarcinoma through the CCNA2-CDK2 complex and AURKA/PLK1 molecule." (PMID 34880385, 2021). "Mechanistically, Gliclazide inhibited the proliferation of lung adenocarcinoma cells possibly by targeting CCNB1, CCNB1, CDK1 and AURKA to induce cell cycle arrest and apoptosis." (PMID 34249701, 2021). "Significant differences in the expression of AURKA and S1PR1 between normal and lung adenocarcinoma (LUAD) tissues were found in the GEPIA2 database; Western blot showed that OSU-2S could affect p-AURKA and S1PR1 protein expression." (PMID 38794152, 2024). "Interestingly, it was found that miRNA-885-3p could result in downregulation of Aurora kinase A (AURKA), thereby inhibiting docetaxel chemoresistance in lung adenocarcinoma." (PMID 36064409, 2022).
lung adenocarcinoma (continued). "Among the lung adenocarcinoma (LUAD) and lung squamous cell carcinoma (LUSC) cases, we found that when compared with non-tumor (N) tissues, the level of AURKA expression was upregulated in tumor (T) tissues." (PMID 32849824, 2020).
leukemia (25 papers, 2012 to 2025). A malignant (clonal) hematologic disorder, involving hematopoietic stem cells and characterized by the presence of primitive or atypical myeloid or lymphoid cells in the bone marrow and the blood. "Treatment with the Aurora kinase A inhibitor alisertib blocked Ph+ leukemia cell proliferation and Aurora kinase A phosphorylation; it also induced G2/M-phase arrest and increased the intracellular levels of reactive oxygen species." (PMID 30197758, 2018). "In addition, these CTLs can kill leukemia cells endogenously expressing AURKA, indicating that the homologous epitopes are naturally processed and presented at a level sufficient for immunotherapeutic applications." (PMID 35664691, 2022). "AURKA-specific CD8(+) T cells can selectively lyse leukemia cells." (PMID 35664691, 2022). "AURKA-specific CTLs can specifically and selectively lyse leukemia cells." (PMID 30622438, 2019). "In this study, we investigated whether inhibiting Aurora kinase A can reduce the viability of Ph+ leukemia cells that are resistant to ABL TKIs." (PMID 30197758, 2018). "The response by the effector cells to endogenous expression of the target peptide were consistent with the results from the peptide-pulsing experiments, confirming the efficacy of the siAUK cells against AURKA peptide/HLA-A*0201 complex levels expressed by AURKA-positive leukaemias." (PMID 27271876, 2016). "However, one of the top candidates responsible for PLK-1 re-upregulation in adult leukemia cells upon volasertib treatment was Aurora kinase A. A number of Aurora kinase A inhibitors have already shown convincing results, for example, alisertib, which is currently undergoing clinical evaluation." (PMID 39684470, 2024). "Therefore, AURKA-TCR-T cell therapy against leukemia is an alternative approach." (PMID 30622438, 2019). "A dendrogram of leukemia patients clustered by hierarchical clustering in the BC CML and normal cell population showed that AURKA and AURKB were increased in BP CML patients compared with normal patients." (PMID 38714583, 2024). "Since the leukemia cell line K-562 was chemosensitive for both aurora kinase inhibitors (GW809897X and GW806742X), we decided to measure the AURKA and AURKB mRNA expression in the ALL patient’s blood cells." (PMID 33277547, 2020). "Cellular experiments demonstrated that both inhibitors induced cell death with caspase activation and cell cycle arrest, however only the GW806742X inhibitor decreased with more efficacy AURKA and AURKB expression in K-562 leukemia cells." (PMID 33277547, 2020). "Therefore, we assessed the impact of KIFC1 inhibitors, as well as inhibitors of the mitotic kinases, aurora kinase A (AURKA) and polo-like kinase 1 (PLK1), on 2 primary Eμ-Ret leukemia samples and the 289 cell line." (PMID 38519798, 2024). "The aim of this study was evaluated the mRNA expression profile of pediatric Acute Lymphoblastic Leukaemia (ALL) patients and the efficacy of two AURKA and AURKB designed inhibitors (GW809897X and GW806742X) in a leukemia cell line as a potential novel therapy for ALL patients." (PMID 33277547, 2020). "However, as the range of suitably responsive tumors is still limited, we have proposed some new options, such as HLA-A*2402-restricted WT1-specific TCR and HLA-A*0201-restricted Aurora kinase A (AURKA)-specific TCR, for the treatment of human leukemias." (PMID 23441216, 2013). "Firstly, it was proved that non-selective AURKA and AURKB inhibitors GW809897X and GW806742X treatment reduced cell proliferation of leukemia cell line (K-562) with a potency constant IC50 of > 5 μM and 1.47 μM, respectively." (PMID 33277547, 2020).
breast tumors (21 papers, 2010 to 2025). "The AURKA gene is a proto-oncogene often overexpressed in malignant breast tumors, and it is involved in the genetic pathway underlying the origin of aneuploidy and loss of centrosome duplication control." (PMID 30104527, 2018). "A remarkable similarity between mouse and human BRCA2-mutated breast tumors was that the peak of both the human (chromosome 20) and mouse (chromosome 2) centered exactly on the Aurora kinase A (AURKA) oncogene." (PMID 20735817, 2010). "Indeed, amplification and overexpression of AURKA (which encodes aurora-A kinase) have been observed in breast tumors and other cancers exhibiting aneuploidy." (PMID 21352579, 2011). "The AURKA gain has been previously associated with BRCA2-mutated breast tumor development but our findings suggest that the functional interaction between AURKA and BRCA2 may be evolutionarily conserved." (PMID 20735817, 2010). "We observed that breast tumors with AURKA amplification had significantly higher gene expression levels than tumors without amplification (p-value<0.001)." (PMID 36717329, 2023). "One excellent example of this is the targeting of NEDD9 as an AURKA stabilizer in ciliary disassembly to potentiate AURKA treatment in breast tumours." (PMID 33860332, 2021). "Following these suggestions, the expression of HMMR and AURKA or TUBG1 in sporadic breast tumors was found to potentially interact, influencing patients’ survival." (PMID 25830658, 2015). "We then confirmed that AURKA expression is enhanced in ductal breast tumors and is a valuable marker of the evolution of the disease." (PMID 24876664, 2014). "In a mouse model, AURKA overexpression was shown to induce breast tumor formation in mammary epithelium." (PMID 23186136, 2012). "We also identified a two-gene expression signature (PLK1 + AURKA) which discriminated between DNA aneuploid and DNA diploid breast tumor samples." (PMID 21352579, 2011). "Five of these genes (NEK2, PLK, BIRC5, TPX2 and AURKA) displayed DNA amplification (or polysomy) in more than 30% of breast tumors." (PMID 21352579, 2011). "Breast tumors showing higher expression of AurkA (fold change >1.5), expressed miR-128 at very low levels (fold change <1.5), conversely tumors showing low levels of AurkA (fold change <1.5), exhibited higher levels of miR-128 (fold change >1.5)." (PMID 27341528, 2016). "Patient’s breast tumour and bone metastasis-derived PDX show amplification of FGFR1, MYC, CCNE2, CCND1 and AURKA." (PMID 32792481, 2020). "Combined expression of HMMR and AURKA, and HMMR and TUBG1 in sporadic breast tumors appeared to influence patients’ survival differentially." (PMID 25830658, 2015). "Analogous to the HMMR setting, rs2426618 is relatively close (∼30 kb) to the promoter region of AURKA/CSTF1, which is active in mammary epithelial cells and differentially ERα-regulated in poor-prognosis breast tumors." (PMID 25830658, 2015). "In this study we have analyzed the expression of MAP9/ASAP and its two partners AURKA and PLK1 in colorectal and breast tumors." (PMID 24876664, 2014). "The PR gene, PGR, and 3 other genes (GATA3, STC2 and GLI3) are increased in their expression, whereas the expression of 6 genes (AURKA, BUB1, CDC20, MKI67, HJURP, and CENPA) is decreased in PR-positive breast tumors." (PMID 22022496, 2011). "Interestingly, Bièche and his team (2011) reported that the mRNA expressions of NDC80 and AURKA were simultaneously higher in breast tumors than in the normal tissues." (PMID 26468983, 2015).